ICOS (inducible T cell costimulator)
Diseases named in the same sentence as ICOS in open-access papers (continued):
Sharing a sentence is not in itself a finding about the gene and the disease.
follicular lymphoma (5 papers, 2017 to 2022). Follicular lymphoma is a form of non-Hodgkin lymphoma characterized by a proliferation of B cells whose nodular structure of follicular architecture is preserved. "Recent studies showed that follicular lymphoma cells generate Treg cells via ICOS/ICOSL cascade and are susceptible to treatment by anti-ICOS/ICOSL therapy." (PMID 30319662, 2018). "In the co-culture system of intertumoral ICOS+CD4+ T cells and ICOS+ Follicular Lymphomas B cells (FL B cells), the ICOS/ICOSL interaction induces the generation of Tregs." (PMID 36211467, 2022). "Recent study showed that follicular lymphoma cells generate Treg cells via ICOS/ICOSL cascade and are susceptible to anti-ICOS/ICOSL therapy." (PMID 28637496, 2017). "The prognosis of follicular lymphoma (FL) patients is suspected to be influenced by TI-Tregs, which comprise activated ICOS+ Tregs that are able to inhibit not only conventional T cells but also FL B cells, which are able to express ICOSL and generate Tregs expressing ICOS." (PMID 32680511, 2020). "In the follicular lymphoma (FL) microenvironment, CXCR5+ICOS+PD1+BCL6+ follicular helper T (Tfh) cells, which closely correlate with FL B cells in neoplastic follicles, play a major role in supporting FL." (PMID 34069564, 2021).
metastatic melanoma (5 papers, 2017 to 2026). A melanoma that has spread from its primary site to another anatomic site. "ICOS expression on Tregs after IL‐2 therapy and the presence of Tregs in tumor infiltrating lymphocytes (TILs) has been associated with poor clinical outcome in metastatic melanoma, however ICOS presence on other TILs has been associated with better prognosis." (PMID 41474629, 2026). "Finally, a retrospective analysis of cancer patients treated for metastatic melanoma revealed a sustained increase in the frequency of ICOS+ T cells in patients who derived clinical benefit from therapy." (PMID 28194010, 2017).
non-small cell lung carcinoma (5 papers, 2016 to 2024). A group of at least three distinct histological types of lung cancer, including non-small cell squamous cell carcinoma, adenocarcinoma, and large cell carcinoma. "The GSE128822 dataset involves gene expression profiles of FACS-sorted Tregs (CD4+CD25+CD127-CCR8+ICOS+ and CD4+CD25+CD127-CCR8-ICOS-) from five surgically resected and cryopreserved human non-small-cell lung cancer carcinomas." (PMID 39273290, 2024). "Meanwhile, in the 12 vs 16 months group, the top five canonical pathways activated by the differentially expressed miRNAs were PI3K signaling, iCOS-iCOSL signaling, inhibition of angiogenesis by TSP1, non-small cell lung cancer signaling, and telomerase signaling." (PMID 33198638, 2020).
T-cell lymphoma (5 papers, 2013 to 2025). "When expressed in mice on a Tet2-/- background, the RHOAG17V mutation identified in 70% of AITL results in T cell lymphomas that partially require ICOS and PI3K signaling for their proliferation and survival." (PMID 36960072, 2023). "Although promising, in vivo human data on therapies targeting the ICOS/ICOS-L pathway cutaneous T-cell lymphoma are still limited." (PMID 36765704, 2023). "In diseases such as T-cell lymphoma, attenuating the effects of ICOS stimulation may be important and, therefore, an ICOS antagonist may be appropriate." (PMID 40297627, 2025). "In T-cell lymphoma carrying the NPM-ALK fusion protein (ALK-TCL), miR-219 was found to target cell-stimulatory receptor ICOS (inducible T-cell co-stimulator or CD278) which was known to promote the proliferation of T-cells." (PMID 23690991, 2013).
antibody deficiency (4 papers, 2009 to 2020). "The ratio of Th1/Th2 cells was significantly elevated compared with ICOS sufficient primary antibody deficiency patients (p = 0.0002) and healthy controls (p < 0.0001)." (PMID 31858365, 2020). "Whereas in the initially published families, ICOS deficiency seemed to produce isolated hypogammaglobulinemia, the recently published patients showed more complex phenotypes with prominent autoimmune features and opportunistic infection profiles." (PMID 28861081, 2017). "Among these families, loss of function mutations of key genes such as ICOS, CD19 and BAFF-R have offered a clear mechanistic rationale for antibody deficiency." (PMID 19775471, 2009).
B-cell lymphoma (4 papers, 2017 to 2022). "This group also implicated the CD8+CD122+ population, suggesting it plays a key role in restricting expansion of CD4+ICOS+ T cells, antibody production, and development of B cell lymphomas." (PMID 28098193, 2017). "As a serum oncogenic biomarker of B-cell lymphoma, miR21 indicated B-lymphoma cell sensitivity to ABT-199 via ICOS/ICOSL-mediated interaction of Treg cells with endothelial cells." (PMID 28637496, 2017). "MiR-21 induced the expression of ICOS on Tregs through the upregulation of p-STAT3, increased the interaction of Tregs with epithelial cells via the ICOS/ICOSL axis, stimulated neoplasm ontogenesis, and also led to the chemoresistance of B-cell lymphoma." (PMID 35464451, 2022). "To our knowledge, we provided the first evidence that miR21 enhanced the interaction of Treg cells with endothelial cells, induced ICOS expression on Treg cells, stimulated tumor angiogenesis via ICOS/ICOSL signaling, and led to chemoresistance of B-cell lymphoma." (PMID 28637496, 2017).
glioblastoma (4 papers, 2019 to 2024). The most malignant astrocytic tumor (WHO grade IV). "CTLA-4 showed stronger associations with PD-1, CD40, and ICOS in patients with glioblastoma in both databases." (PMID 31911758, 2020). "In glioblastoma, elevated ICOS levels within TMEs, compared to peripheral blood, indicate its prognostic value." (PMID 38342925, 2024). "Increased ICOS expression post-treatment potentially indicates immunotherapy responsiveness in glioblastoma." (PMID 38342925, 2024). "Through investigation of expression status and molecule function of the ligand of ICOS (ICOSLG) in glioblastomas, they concluded that ICOSL, via conjugation with ICOS, was associated with more malignancy of glioblastoma." (PMID 36276141, 2022). "This complexity highlights ICOS as a therapeutic target in glioblastoma." (PMID 38342925, 2024).
helminth infections (4 papers, 2013 to 2025). "Studies have also demonstrated that ICOS can promote the proliferation and function of Foxp3+ Treg cells during various helminth infections." (PMID 40316996, 2025). "ICOS knockout miceareincapable of controlling viral or worm infections owing toimpaired Th1 and Th2 responses, respectively." (PMID 25590646, 2015). "Thus, ICOS regulates Type 2 immunity in a tissue-specific manner, and plays a key role in driving Foxp3+ Treg-cell expansion and function during helminth infections." (PMID 23319295, 2013). "Thus, ICOS controls Type 2 immunity in a tissue-specific manner, and plays a key role regulating Foxp3+ Treg-cell induction, maintenance and function during helminth infection." (PMID 23319295, 2013). "Thus, ICOS regulates Type 2 immunity in a tissue-specific manner, and plays a key common role driving Foxp3+ Treg-cell expansion and function during distinct helminth infections." (PMID 23319295, 2013). "In this study we tested the hypothesis that ICOS is required for the induction and function of Foxp3+ Treg-cell responses during helminth infection." (PMID 23319295, 2013). "To determine whether ICOS is required for the generation of Foxp3+ Treg-cell responses during helminth infection, we infected C57BL/6 ICOS−/−33 and WT mice with H. polygyrus or S. mansoni." (PMID 23319295, 2013). "Furthermore, other co‐inhibitory molecules can also be found on the surface of Tregs responding to helminth infection including PD‐1 and ICOS, which indicate that not only are Tregs expanded during helminth infection but are also potentially more actively suppressive." (PMID 32153025, 2020). "The expansion of CD4+Foxp3− Teff cells was also reduced in the absence of ICOS as observed in other helminth infections 28–31." (PMID 23319295, 2013). "Additionally in the review, Tregs during helminth infection express high levels of CTLA‐4, PD‐1 and ICOS on their surface, indicating that these cells potentially represent a more active Treg population that would be efficient suppressors of inflammatory diseases." (PMID 32153025, 2020).
idiopathic pulmonary fibrosis (4 papers, 2018 to 2025). Idiopathic pulmonary fibrosis (IPF) is a nonneoplastic pulmonary disease that is characterized by the formation of scar tissue within the lungs in the absence of any known cause. "Additionally, the ratio of Tim‐3+, ICOS+, and OX40+ in CD4+ T cells is significantly higher in patients with CT features of usual interstitial pneumonia compared with the non‐ILD group, which aligns with the findings of this study." (PMID 40165483, 2025).
liver cancer (4 papers, 2018 to 2024). An epithelial or non-epithelial malignant neoplasm that arises from the liver. "In liver cancer, the ICOS/ICOS‐L pathway is involved in the promotion of immune tolerance by producing T‐regulatory type 1 cells (Tr1)." (PMID 38506253, 2024). "To summarize, because ICOS can restrain the proliferation and invasion of liver cancer cells in vitro, ICOS is expected to become a potential treatment target for liver cancer." (PMID 29316975, 2018). "Studies regarding ICOS in liver cancer, however, are far from sufficient, and the literature related to cell or animal experiments to date have limited our further understanding of the pathogenesis of liver cancer." (PMID 29316975, 2018). "The present study provides the experimental and theoretical bases for exploring the effect of the ICOS gene in liver cancer and also provide a new scientific perspective to illustrate the pathogenesis of liver cancer." (PMID 29316975, 2018). "Notably, ICOS was expressed at higher levels in both liver cancers than in PDA, suggesting tumor-tissue specific features and a dysfunctional T cell state in PDA." (PMID 36798126, 2023). "Our experimental results also further confirmed the role of P13K in liver cancer cells, and suggested that ICOS may regulate the proliferation and invasion of HepG2 liver cancer cells, and apoptosis through regulating the expression of phosphorylation PI3K and the expression of AKT." (PMID 29316975, 2018).
lymph node metastasis (4 papers, 2011 to 2024). "Moreover, ICOS protein levels were significantly associated with different stages, lymph node metastasis, tumor size, and recurrence status." (PMID 37850501, 2023). "In OSCC and HNSCC, higher ICOS or lower CD276/ICOS is a good prognostic marker for patient survival and lymph node metastasis." (PMID 39104717, 2024). "Interestingly, lymph node metastasis was associated with the overexpression of various checkpoints, including PD-L2, TIGIT, TIM-3, ICOS, PD-L1, and CD27." (PMID 33414407, 2021). "However, the expression of ICOS significantly decreased in TNM stages, invasion depth, lymph node metastasis, and distant metastasis." (PMID 39104717, 2024).
mesothelioma (4 papers, 2018 to 2022). A usually malignant and aggressive neoplasm of the mesothelium which is often associated with exposure to asbestos. "Additional co-inhibitory and co-stimulatory molecules such as T-cell immunoglobulin and mucin-domain containing-3 (TIM3, also known as HAVCR2), lymphocyte activation gene 3 (LAG3) and inducible T cell co-stimulator (ICOS) are being investigated in mesothelioma." (PMID 32226777, 2020). "They further raised that the CD26high-ICOS-CAR-T cells with Th1/Th17 phenotypes elicited potent tumor elimination and durable persistence, and even outperformed CD8 CAR-T cells in the mesothelioma animal model." (PMID 31379876, 2019). "In summary, these findings show that following autologous DC therapy in mesothelioma patients the frequencies of circulating CD4 T cells expressing HLA-DR, PD-1 or ICOS, as well as CD8 T cells expressing the co-inhibitory receptor LAG3 are significantly increased." (PMID 30245692, 2018).
Multiple myeloma (4 papers, 2012 to 2025). "Furthermore, in a study showing the importance of NK cell dysfunction in multiple myeloma, ICOS expression levels were found to be higher in bone marrow CD56bright NK cells from relapsed/refractory patients, while TIGIT and TIM3 were increased." (PMID 39201462, 2024). "In myeloma, tumor cells with high expression of ICOSLG have stronger proliferation ability and can activate ICOS-ICOSLG pathway to inhibit tumor immune response." (PMID 37842091, 2023).
myasthenia gravis (4 papers, 2021 to 2024). Myasthenia gravis (MG) is a rare, clinically heterogeneous, autoimmune disorder of the neuromuscular junction characterized by fatigable weakness of voluntary muscles. "Increased frequency of ICOS+ or ICOShigh cTFH cells standing for an “activated” phenotype has been found in patients with autoimmunity such as RA, SS, myasthenia gravis (MG), SLE, autoimmune thyroid diseases, and all autoimmune pathologies partially caused by autoantibodies." (PMID 34552387, 2021).
Obesity (4 papers, 2022). Accumulation of substantial excess body fat. "In prior studies, we found that diet-induced obesity was associated with suppressed immune activity in the murine tumor microenvironment coincident with elevated frequencies of intra-tumoral Tregs expressing high levels of activation markers (CD44, ICOS) and suppressive mediators (PD-1, Lag3)." (PMID 36289552, 2022).
psoriasis (4 papers, 2016 to 2022). An autoimmune condition characterized by red, well-delineated plaques with silvery scales that are usually on the extensor surfaces and scalp. "The cTfh cells were activated in psoriasis with the expression of ICOS, Ki-67, PD-1, and HLA-DR at higher levels and increased production of interleukin (IL)-21, IL-17, and interferon (IFN)-γ." (PMID 34512732, 2021). "cTfh cells are activated in psoriasis, expressing high levels of ICOS, PD-1, HLA-DR, and Ki-67 and secreting increased levels of IL-21, IL-17, and IFN-γ." (PMID 27774460, 2016). "As a result, immunostimulatory genes showed higher expression levels within psoriasis than normal tissues, such as CD86, CD48, TNFRSF4, TNFRSF25, ICOS, and CXCR4." (PMID 36685512, 2022). "Our results showed both increased frequency and activation (indicated by higher expression of ICOS, PD-1, HLA-DR, and Ki-67 and increased production of IL-21, IL-17, and IFN-γ) of cTfh cells in psoriasis patients." (PMID 27774460, 2016).
sarcoma (4 papers, 2019 to 2025). A usually aggressive malignant neoplasm of the soft tissue or bone. "Coexpression of PD-1 and ICOS had previously been shown to mark neoantigen-reactive CD4+ Th cells in a murine sarcoma tumor model." (PMID 35439168, 2022). "A search of the literature indicated few studies investigating 4–1BB or other costimulatory molecules, such as OX40, GITR, or ICOS across sarcoma subtypes." (PMID 35558159, 2022). "Our proposed strategy to enrich for human tumor–reactive CD4+ Th cells is supported by a previous study in a mouse sarcoma model showing that neoantigen-reactive CD4+ Th cells found in the tumor expressed both PD-1 and ICOS." (PMID 35439168, 2022). "Our study is in line with previous studies on other tumor models like the T3 methylcholanthrene-induced sarcomas showing that inhibitory markers like PD-1 and TIM-3 and activating receptors like ICOS are co-expressed on tumor-specific T cells." (PMID 31412943, 2019). "Analysis of the transcript levels of the costimulatory receptors OX40/TNFRSF4, ICOS, and GITR/TNFRSF18 indicated that ICOS and GITR transcripts were not highly expressed in any sarcoma subtype relative to other cancers in the TCGA dataset." (PMID 35558159, 2022).
schistosomiasis (4 papers, 2015 to 2024). An infectious disease caused by parasitic trematodes of the genus Schistosoma that colonize human blood vessels and release eggs that can cause granulomatous reactions leading to acute (swimmer's itch or acute schistosomiasis syndrome) or chronic disease. "In comparison to C57BL/6 mice, ICOSL-KO infected mice showed reduced symptoms at 7–12 wpi, indicating that ICOSL/ICOS signaling can influence liver fibrotic lesions in schistosomiasis." (PMID 39044218, 2024). "While the iCOS-iCOSL pathway has been reported to have an effect on fibrosis and hepatopathology in mice infected with schistosomiasis, its exact role is debated." (PMID 32636844, 2020). "To further elucidate the role of ICOSL/ICOS signaling in the process of schistosomiasis-induced liver fibrosis, we concurrently established both S. japonicum-infected C57BL/6 and ICOSL-KO mice and monitored the liver pathological changes at different timepoints postinfection." (PMID 39044218, 2024). "Here, usingthe ICOSL KO mice as a model of schistosomiasis,westudied the role of the ICOSL/ICOS interaction in the mediation of the Th17 response in host granulomatous inflammation, particularly in liver fibrosis during S. japonicum infection." (PMID 25590646, 2015). "The expression of ICOS might not be detectably upregulated in acute schistosomiasis patients because their livers have only slight damage." (PMID 27266984, 2016). "Also, a clearly positive correlation between the presence of IL-17-producing cells and ICOS expression in ICOSL KO mice was observed, which suggested that Th17 cells were involved in the pathological tissue remodeling in liver fibrosis induced by schistosomiasis." (PMID 25590646, 2015). "Importantly, there was a clearly positive correlation between the presence of IL-17-producing cells and ICOS expression in ICOSL KO mice, and additional results indicated that Th17 was involved in the pathological tissue remodeling in liver fibrosis induced by schistosomiasis." (PMID 25590646, 2015).
uveitis (4 papers, 2017 to 2023). An inflammatory process affecting a part of or the entire uvea. "Combined inhibition of CD28 and inducible T cell costimulator (ICOS) pathways with acazicolcept (ALPN-101) represents a potential new treatment for uveitis." (PMID 36976157, 2023). "In a murine model of autoimmune uveitis, the in vivo blocking of IGOSLG signaling reduced disease severity and led to a smaller number of inflammatory infiltrates in the retina, suggesting that ICOS-ICOSLG interaction plays a critical role in uveitis pathogenesis." (PMID 33806940, 2021). "Interestingly, a high expression of ICOS on CD4+ T cells has been described in BD patients with active uveitis, suggesting a role in the pathogenesis of uveitis, possibly through upregulation of IFN-g, IL-17, and TNF." (PMID 29850627, 2018). "Together, these data show that in eyes with uveitis the majority of CD4+, and to a lesser extent CD8+, T cells express the costimulatory receptors CD28 and ICOS, and treatment with acazicolcept provides significant blockade of these receptors on ocular infiltrating T cells." (PMID 36976157, 2023). "The VNAR domain with the highest potency in cell-based blocking of ICOS/ICOSL interaction was fused to the Fc portion of human IgG1 and was tested in vivo in a mouse model of interphotoreceptor retinoid-binding protein-induced uveitis." (PMID 28993766, 2017).
acute GVHD (3 papers, 2017 to 2020). "Previous studies have shown that ICOS−/− T cells have reduced IFN-γ yet elevated IL-4, which resulted in alleviated acute GVHD (aGVHD); blocking ICOS confirmed this reduced GVHD severity." (PMID 29988391, 2018).
breast tumors (3 papers, 2017 to 2023). "Our data indicated that ICOS expression is correlated with the degree of malignancy of breast tumor and the survival of patients with TNBC." (PMID 38127899, 2023). "ICOS expression was found on tumor infiltrating and proliferative Tregs, and was suggested to be associated with poor prognosis in a cohort of 120 patients with invasive nonmetastatic breast tumors." (PMID 38127899, 2023).